MTOR (mechanistic target of rapamycin kinase)
Diseases named in the same sentence as MTOR in open-access papers (continued):
Sharing a sentence is not in itself a finding about the gene and the disease.
breast cancer (continued). "Some PI3K and mTOR inhibitors have been approved by regulatory authorities for the treatment of specific breast cancer patient populations, and many new-generation PI3K/mTOR inhibitors and AKT isoform inhibitors have also been shown to have good prospects for cancer therapy." (PMID 36010585, 2022). "Moreover, miR-100 and miR-16 shuttled by BMMSC-EVs suppressed breast cancer cells angiogenesis in vitro through modulating the mTOR/HIF-1α/VEGF signaling axis, suppressed angiogenesis by down-regulating VEGF expression in breast cancer cells, respectively." (PMID 35915054, 2022). "Patients with CDKI-resistant breast cancer cells have become more dependent on PI3K/AKT/mTOR signaling pathways rather than ERα signaling for oncogenesis." (PMID 36358806, 2022). "CDK4/6I-resistant breast cancer cell lines show reactivation of phosphorylated-Rb and E2F, which may occur via the CDK or the mTOR pathways." (PMID 36358806, 2022). "Moreover, miR-21 regulates the development of breast cancer by promoting breast cancer cell growth, invasion, and migration by suppressing the action of PTEN which is a major negative regulator of the PI3K/AKT/mTOR signaling pathway." (PMID 35684480, 2022). "The impact of Dyns inhibition in vasopressin stimulated or AKT/mTOR inhibited breast cancer cells was not addressed." (PMID 35307810, 2022). "In breast cancer, miR-21 is a key miRNA in the promotion of proliferation and dysregulation of apoptosis by inhibiting genes such as PTEN, SMAD7, and PDCD4, ultimately leading to deregulation of the PI3K/Akt/mTOR pathway." (PMID 36555616, 2022). "Herein, a drug delivery nanoplatform equipped with dual PI3K/mTOR inhibitor Dactolisib (NVP-BEZ235, BEZ235) and CAIX inhibitor 4‐(2‐aminoethyl) benzene sulfonamide (ABS) was designed to mitigate hypoxic adaptation and improve breast cancer treatment." (PMID 35413842, 2022). "In the pathogenesis of breast cancer, the phosphatidylinositol 3-kinase (PI3K)-protein kinase B (PKB/AKT)-mammalian target of rapamycin (mTOR) axis is a key regulator of cell proliferation, growth, survival, metabolism, and motility, making it an interest and therapeutic target." (PMID 35565291, 2022). "The mTOR pathway plays a role in breast cancer cell proliferation and anti-cancer drug resistance and was also reported to crosstalk with the NOTCH signaling pathway in several malignant cells, including breast cancer cells." (PMID 35163478, 2022). "Moreover, CENPF also promotes breast cancer progression and bone metastasis by activating the AKT/mTOR signaling pathway." (PMID 35141213, 2021). "Indeed, the PI3K/Akt/mTOR pathway is the most commonly upregulated pathway in HR- and HER2+ breast cancers, being involved in many aspects of cell growth, proliferation, survival, metabolism, and immune response regulation." (PMID 34706703, 2021). "The PPI networks of the differentially methylated genes of the three comparisons were enriched in the mTOR signaling pathway, MAPK, autophagy, apoptosis, and PI3K-Akt signaling pathway, mitophagy, pancreatic, prostate, and breast cancers in addition to chronic myeloid leukemia pathways." (PMID 33501605, 2021). "Finally, we also detected a modulation of genes that have been identified as tumor suppressors in other cancer types, including OGN, a gene that is downregulated in the breast cancer and that functions as PI3K/AKT/mTOR suppressor." (PMID 34012923, 2021). "Also, in breast cancer samples from The Cancer Genome Atlas (TCGA), p-mTOR expression was also correlated with p-AKT, p-p70S6K, and a mTOR signature (r = 0.21–0.45) that was derived from expression levels of seven phosphoproteins in the pathway." (PMID 34330319, 2021). "It has also been reported that phospho-AKT binds to and phosphorylates YB-1 while mTOR does not phosphorylate YB-1 protein in breast cancer." (PMID 34696665, 2021).
breast cancer (continued). "For example, Results of studies suggest autophagy inducers including rapamycin and its derivatives which are known inhibitors of mTOR, can also prevent mTOR-dependent cell proliferation via induction of cell cycle arrest in MDA-MB-231 breast cancer cells and cell lymphoma." (PMID 34660642, 2021). "In addition, miR-100 delivered by MSC-Exos was able to inhibit angiogenesis in vitro by regulating the mTOR/HIF-1α/VEGF signaling axis in breast cancer cells, thereby influencing the behavior of breast cancer cells." (PMID 35186913, 2021). "As previously discussed, HER2 hyperactivity promotes mTOR pathway-dependent up-regulation of glycolytic enzymes, indicating that mTOR is a major contributor to the enhanced glycolytic activation observed in HER2-positive breast cancer." (PMID 34208071, 2021). "Additionally, there are many targeted small molecule inhibitors under clinical trials for the treatment of breast cancer, such as the CDK4/6 inhibitor palbociclib, the PI3K/Akt/mTOR pathway inhibitor pictilisib, the HDAC inhibitor CUDC-101." (PMID 33986665, 2021). "Understanding the relationship between the HER2-Akt-mTOR pathway, glycolysis, and CDK4/6 may pave the way for improved therapies to treat HER2-positive breast cancer and overcome drug resistance." (PMID 34208071, 2021). "Accordingly, the inhibition of ETS transcription Factor ELK3 (ELK3), which is frequently overexpressed in aggressive breast cancers, led to PI3K/AKT/mTOR activation, which in turn enhanced the chemosensitivity of MDA-MB-231 cells to doxorubicin by inhibiting protective autophagy." (PMID 34207792, 2021). "Fortunately, substantial progress has been made after major advances in our understanding of the biology of ER+/HER2– breast cancer in the past 20 years, such as the development of CDK4/6 inhibitors, mTOR inhibitors, PI3Kα inhibitors and histone deacetylase inhibitors." (PMID 33676449, 2021). "SLC39A7, also known as ZIP7, is activated by phosphorylation-mediated zinc release from intracellular stores, drives major pathways, such as MAPK, mTOR and PI3K-AKT, that are involved in cell survival and proliferation, and it was reported to be overactivated in breast cancer and cervical cancer." (PMID 34178683, 2021). "Furthermore, our results demonstrate that MLST8 is required for the assembly and activity of both MTOR complexes and suggest MLST8 is a viable therapeutic target in breast cancer." (PMID 34529665, 2021). "We postulated that an inhibitor that inhibited both mTOR and PI3Ks might be more effective that PI3K inhibition alone when combined with ICI therapy for breast cancer treatment." (PMID 34069042, 2021). "In breast cancer, regulatory feedback loops between the IGF axis and the mTOR/PI3K/AKT pathway may limit the efficacy of mTOR inhibitor/endocrine therapy combinations due to compensatory IGF ligand-driven signalling." (PMID 33451345, 2021). "However, a combination of endocrine therapy with other signaling pathways like PI3K/AKT/mTOR and Ras/Raf/MEK/ERK and coregulatory factors targeted agent should be the focus of future treatment, especially in endocrine-resistant breast cancer." (PMID 33841325, 2021). "For example, PTEN-deficient breast cancer cells are resistant to the pan-PI3K inhibitor GDC-0941 and PI3K/mTOR dual inhibitor BEZ-235, unlike those harboring mutations in PIK3CA and HER219–21." (PMID 33431808, 2021). "In breast cancer, IL-6 pre-treatment followed by SIRT1 activation by SRT1720 combined with dual PI3K/mTOR inhibitor NVP-BEZ235 obviously increased sensitivity of the cancer stem cells to radiation, so that late stage breast cancer cells therapeutic effect was effectively improved." (PMID 33790792, 2021). "Using MMTV-PyMT (MMTV-polyoma virus middle T) transgenic mice and breast tumor cell MCF-7, we show that both exogenous and endogenous CE can increase mammary tumor growth, that CE upregulates the AKT/mTOR pathway, and that CE synthesis blockade suppresses this signaling pathway." (PMID 34201030, 2021).
breast cancer (continued). "Increased PI3K/AKT/mTOR signaling through IGFIR activation is suggested to make breast cancer cells independent of ER signaling for proliferation and survival, conferring endocrine resistance." (PMID 34606580, 2021). "In breast cancer cells, hyperactivation of signaling pathways such as phosphoinositide 3-kinase–AKT– (PI3K/AKT/mTOR), MAPK, and hepatocyte growth factor (HGF)/Met (hepatocyte growth factor receptor (HGFR)) increases cell growth, proliferation, survival, and cancer hallmarks." (PMID 34768930, 2021). "As the mechanistic target of rapamycin (mTOR) pathway and glycolysis also contribute to supporting tumor recurrence and chemoresistance, these signaling pathways have become appealing targets for HER2-positive breast cancer therapy." (PMID 34208071, 2021). "It was stated that the average expression level of the PIK3CA, PIK3R1, PTEN genes in the group of breast cancer patients is lower in comparison to the control group, while the average expression level of the AKT1 and mTOR genes in the studied group was higher in comparison to the control group." (PMID 33669698, 2021). "Other potentially actionable mutations we identified were nonsynonymous mutations in PIK3CA and TSC1, also annotated in both COSMIC and OncoKB, and shown to be clinically targetable in breast cancer through PI3K inhibition and in central nervous system cancers with mTOR inhibition, respectively." (PMID 34464379, 2021). "This is consistent with studies on breast cancer cells and on mutant transgenic mice, showing that cytoplasmic SCRIB promotes cancer development by affecting subcellular localization of PTEN and activation of the Akt/mTOR/S6 kinase signaling pathway." (PMID 34503271, 2021). "Everolimus is an mTOR inhibitor and is widely used to treat NETs, RCC, TSC, and breast cancers." (PMID 34572837, 2021). "Another study recently reported that MDSC in breast cancer microenvironment could promote EMT, migration, and invasion of breast cancer cells by activating the PI3K-Akt-mTOR pathway." (PMID 34689842, 2021). "Not surprisingly, the PI3K/Akt/mTOR pathway and different receptor tyrosine kinases (RTKs) are the major targets for treating breast cancer." (PMID 33435254, 2021). "In another study, lactoferrin was reported to induce cell cycle arrest and inhibit the mTOR signalling pathway, thereby inducing stress, but not apoptosis of breast cancer cell lines." (PMID 34236134, 2021). "PI3K/Akt/mTOR is a major pathway that participates in the regulation of cell survival and proliferation, and the essential genes of the PI3K/Akt pathway, PIK3CA, AKT1, AKT2, and PTEN, are often altered in breast cancer." (PMID 33435254, 2021). "Similarly, an investigation in human breast cancer cells found that migration was also affected through JNK, Akt and mTOR signalling following treatment with UA." (PMID 33530486, 2021). "The top 20 possible drugs that could reverse the breast cancer lung metastasis signature were presented, including IGF-1 inhibitor, mTOR inhibitor, PI3K inhibitor, SRC inhibitor, aurora kinase inhibitor, and JAK inhibitor." (PMID 35111673, 2021). "However, several clinical trials explore the inhibition of the PI3K/AKT/mTOR pathway, which is commonly altered in TNBC or in resistant ER+ or HER2+ breast cancer subtypes." (PMID 34207792, 2021). "In addition, tanshinone IIA can trigger caspase activation and cell cycle arrest in breast cancer cells, along with a forceful inhibition of ERK, mTOR, and protein kinase C activities." (PMID 34575983, 2021). "Taken together, our results reveal a unique action mechanism of CSNK1G2 on PI3K/AKT/mTOR/S6K and ERK signaling pathways in breast cancer cells and provide insight into how the target selectively controls and contributes to cell survival in different human breast cancer cell types." (PMID 33861751, 2021).
breast cancer (continued). "In addition, in vitro and in vivo studies indicated that everolimus combined with metformin synergistically inhibited breast cancer cell growth, clonogenicity, PI3K/mTOR signaling activity, mitochondrial respiration, and xenograft tumor growth." (PMID 34572837, 2021). "Based on the reported response of 231-BO cells to combined AKT/mTOR inhibition in vitro, we suggest that an isoform-specific inhibition of AKT could be a promising therapeutical approach in bone metastasis of breast cancer." (PMID 33670586, 2021). "Beyond drugs that directly target proteins such as ER, EGFR, HER2, MET, PI3K, AKT, mTOR, and those of the MAPK pathway, anti-apoptotic protein inhibitors (BH3 mimetics) are now being evaluated as new targeted therapies for breast cancer as increased anti-apoptotic protein levels have been reported." (PMID 34359829, 2021). "In conclusion, we demonstrated that GABARAP suppressed the proliferation and invasion of breast cancer cells via regulation of the EMT in vitro and in vivo, and the mechanism may be related to regulation of the AKT/mTOR pathway." (PMID 33591943, 2021). "Therefore, we conclude that SGLT1 is overexpressed in HER2+ breast cancer, thereby promoting cell proliferation and shortening survival by activating PI3K/Akt/mTOR signaling." (PMID 32377271, 2020). "We observed a significantly decreased expression of p-Akt, p-PI3K, p-mTOR and subsequent decreased expression of FOXO, Cyclin D1 and Bcl-2 following levobupivacaine treatment which correlated with decreased breast cancer cells proliferation and increased apoptosis." (PMID 32807213, 2020). "In addition, adipocyte-derived conditioned media induced phosphorylation of AKT and mTOR and upregulated the expression of target genes of the PI3K-AKT-mTOR pathway including IL6, IL1β, IL1α and TNFα in breast cancer cells." (PMID 32201525, 2020). "We showed that multiple metabolic rewiring with concomitant mTOR hyperactivity is an unfavourable prognostic sign in breast cancer independent of subtype." (PMID 32899149, 2020). "It is conceivable that activation of PKCε, Akt, and mTOR signaling contributes to breast cancer when cells are not dependent on autophagy to survive, but PKCε can promote cell survival by inducing autophagy when cells are challenged with stress." (PMID 32549199, 2020). "Interestingly, the PI3K/Akt/mTOR pathway appears as a recurrent theme in many studies of BM, in not only NSCLC but other cancers with a proclivity for BM such as breast cancer and melanoma." (PMID 32093103, 2020). "Given that the standard-of-care for many ER+/HER2− breast cancers is now hormone therapy in combination with a CDK4/6 inhibitor, there is a strong rationale to suggest inhibitors of PI3K/mTOR signaling may also be active in this arena." (PMID 32795346, 2020). "Thus, we have chosen to evaluate the preclinical efficacy of the novel dual PIM and PI3K/mTOR inhibitor, IBL-302 in breast cancer as described herein." (PMID 32042115, 2020). "However, another study found hypoxic TAMs in lung and breast cancer mouse models to upregulate regulated in development and DNA damage responses 1 (REDD1), an inhibitor of mammalian target of rapamycin (mTOR) and thereby decreasing glycolysis." (PMID 33171762, 2020). "Besides the mTOR inhibition, oral inhibitors for PI3K isoforms have been established for the treatment of HR+ breast cancer." (PMID 32461963, 2020). "In addition, the role of MUC1 expressing level in affecting drug efficiency need to be validated with different kind of canine mammary tumors, and the molecular mechanism of interactions between MUC1 and PI3K/Akt/mTOR needs to be investigated as well." (PMID 33375426, 2020).
breast cancer (continued). "Similarly, a study showed that miR-100-rich human MSCs exosomes reduced the expression of VEGF in breast cancer (MCF-7 and MDA-MB-231) in a dose-dependent manner by modulating mammalian target of rapamycin (mTOR)/hypoxia-inducible factor-1α (HIF-1α) signaling." (PMID 33374978, 2020). "We quantified metastases 8 weeks later using HLA staining and determined that pre-exposure to salubrinal increased the initiation of metastatic colonies similar to that observed in response to INK, suggesting that mTOR and ISR crosstalk facilitates the emergence of breast cancer cell plasticity." (PMID 32427827, 2020). "In hormone-receptor-positive (HR+), human epidermal growth factor receptor 2-negative (HER2−) breast cancer CDK4/6 inhibitors and mammalian target of rapamycin (mTOR) inhibitors are the most widely used targeted therapies, adding significant benefit to baseline endocrine therapy." (PMID 32565737, 2020). "In the previous study, acidification reduces circadian genes through the mTOR signaling pathway, but it is not well known yet in breast cancer, and it is not enough to explain the mTOR signaling pathway alone." (PMID 32316196, 2020). "Using Bayesian inference, a mathematic framework, researchers have found that combination therapy targeting mTOR and STAT3 may be the best therapeutic target in breast cancer." (PMID 32111215, 2020). "In breast cancer, CBD inhibited AKT and mTOR signaling inducing autophagic cell death." (PMID 32751388, 2020). "This modulatory effect of HT could contribute to counteract breast cancer progression as high levels of PI3K, pAkt and p-mTOR are predictors of an adverse outcome in breast cancer patients." (PMID 32286485, 2020). "in breast cancer cell lines, inhibition of p70S6 kinase, a downstream target of mTOR, was achieved in all NEN cell lines, but did not correlate with their susceptibility as measured by cell viability and survival." (PMID 33628728, 2020). "In T47D breast cancer cells, DEX was shown to affect the PI3K/AKT/mTOR pathway that could also be a possible target in thyroid cancer cells responsible for the suppression of spheroid formation." (PMID 32033410, 2020). "The anti-tumor activity of disulfiram was limited in CIPp cells with overexpressed MUC1, along with little interference of disulfiram on the activation of PI3K/Akt/mTOR, indicating that the level of MUC1 affected the efficiency of disulfiram in treating canine mammary tumors." (PMID 33375426, 2020). "In tamoxifen-resistant LCC2 and LCC9 breast cancer cell lines, rate of glycolysis is higher than that in MCF-7S cells, and HIF-1 was found to be activated through the Akt/mTOR signaling pathway, with phosphorylated AMPK being decreased without hypoxic conditions." (PMID 32252351, 2020). "Along those lines, mTOR signaling that interferes with breast cancer growth has been shown to be the target of miR-99a, whereas miR-122 plays an important role in inhibiting tumorigenesis through targeting IGF1R and regulating the PI3K/Akt/mTOR/p70S6K pathway." (PMID 32276464, 2020). "mTOR activity can also be stimulated, independently of the PI3K pathway, by CDK4 and PIM kinases, both of which have been identified as potential mechanisms of resistance to PI3K inhibitors in breast cancer." (PMID 32391118, 2020). "Moreover, metformin enhanced tamoxifen-mediated induction of apoptosis in breast cancer cells via the bax/bcl-2 apoptotic pathway and the AMPK/mTOR/p70S6K growth pathway." (PMID 31780804, 2019). "Other investigators also found that hyperglycemia promoted the proliferation of malignant breast cancer epithelial cells by increasing leptin/insulin-like growth factor-1 receptor (IGF-1R) signaling and activating the Protein Kinase B/mechanistic target of rapamycin (AKT/mTOR) pathway." (PMID 31337431, 2019). "The main therapeutic targets for breast cancer taken for the study were ERα, PR, EGFR, and mTOR." (PMID 31673107, 2019).